CD44 (CD44 molecule (IN blood group))
Diseases named in the same sentence as CD44 in open-access papers (continued):
Sharing a sentence is not in itself a finding about the gene and the disease.
glioma (continued). "CD44 is one of the glioma stem cell markers with multifunctional activity, including cell adhesion and signal transductions, resulting in participation in promoting migration and invasion in various cells including glioma stem cells." (PMID 40002787, 2025). "Upon the stimulation by serum, which has been known as an inducer of GIC differentiation, the GIC spheres increase cellular proliferation, motility, and adhesion to the culture dishes and upregulate the glial cell markers such as GFAP (glial fibrillary acid protein) and the glioma marker CD44." (PMID 38309500, 2024). "By using CD44-specific blocking antibodies or aptamer, it may be possible to reverse the immunosuppression on gliomas through the blockage of CD44 signaling." (PMID 38515213, 2024). "Both stRNA-seq and scRNA-seq indicate that BRMS1 + microglia may promote the malignant transformation of glioma cells through SPP1/CD44-mediated intercellular interactions." (PMID 39143438, 2024). "Moreover, upregulation of L1CAM and CD44 expression in surviving glioma tumor cells that are detected after aptamer exposure is often associated with increased cell migration ability." (PMID 38256907, 2024). "Interestingly, binding of OPN with CD44 leads to cleavage of the CD44 intracellular domain by γ-secretase, which in turn governs the stemness characteristics in glioma." (PMID 39062100, 2024). "A similar significance of SPP1/CD44-related signals has been suggested in glioma and HCC56,57." (PMID 38521868, 2024). "Amongst myeloid cells, CD44-positive cells appear to have a role in glioma invasion." (PMID 38473812, 2024). "Interestingly, in glioblastoma, the expression of the transmembrane glycoprotein CD44 relates to the tumor grade; moreover, glioma cell-derived EVs contain high levels of CD44, thus allowing attraction of MMPs that promote ECM remodeling." (PMID 39194524, 2024). "In addition, both DM-α-KG and SP promoted the differentiation of glioma cells through elevated GFAP expression and reduced Nestin, CD133, and CD44 expression, suggesting that α-KG accumulation can promote the differentiation of glioma cells." (PMID 39872214, 2024). "Additionally, it had been demonstrated that SPP1/CD44 interaction mediated crosstalk between macrophages and glioma cells." (PMID 38346944, 2024). "The results of immunoblotting showed that co-culture with HMC3 significantly increased the expression of CD44 in glioma cells, thereby activating the PI3K/AKT signaling pathway, leading to a significant downregulation of Bax and cleaved-caspase 3, and a significant upregulation of Bcl-2." (PMID 39143438, 2024). "Among the most prominently upregulated proinvasive factors in glioma is CD44, which takes place early during gliomagenesis and promotes glioma invasion into the neuropil through interaction with its ligand hyaluronan in the extracellular matrix (ECM) of the brain." (PMID 39530733, 2024). "In high-grade gliomas, including glioblastomas, CD44 also may serve as an effective marker for detailed diagnosis and clinical prediction." (PMID 36835465, 2023). "CD44 overexpression could be relevant in regulating the highly invasive behaviour of gliomas, and NSC‐CM‐mediated CD44 inhibition may reduce the invasive capabilities of glioma cell lines." (PMID 37410396, 2023). "CD44 is a receptor for hyaluronic acid and is frequently expressed in glioma stem cells." (PMID 38275375, 2023).
glioma (continued). "Data demonstrated a significantly positive association between CD44 expression level and stromal score, immune score, and ESTIMATE score according to the TCGA dataset, indicating that changing stromal and infiltrating immune cells, CD44 can affect the glioma microenvironment." (PMID 36776876, 2023). "The results of western blotting showed that the expression of Wnt/β‐catenin signalling pathway‐related proteins, including β‐catenin, c‐Myc, cyclin D1, CD44 and Met, was significantly lower in glioma cells treated with NSC‐CM than in those treated with the control medium." (PMID 37410396, 2023). "Our finding indicated that RUNX1 could potentially promote glioma proliferation and migration by up-regulating the expression of CD44." (PMID 36776876, 2023). "A few studies have focused on the molecular and clinical pattern of CD44 expression in gliomas." (PMID 36776876, 2023). "CD44 was found as an important regulator of macrophage and immunotherapy in gliomas." (PMID 36776876, 2023). "Glioma tissue is characterized by significantly high immunoreactivity with anti-CD44 antibody compared to normal brain tissues and an increased amount of hyaluronic acid, up to twenty times more than in healthy adult brain; that is akin to the fetal central nervous system." (PMID 36835465, 2023). "Impressively, nano-flow cytometry revealed increased CD44/BSG double-positive EVs in EGFRvIII-overexpressing glioma cells compared with their parental cells, which represents a cellular phenotype with strong co-localization in spike-like invadopodia on the plasma membrane." (PMID 37823055, 2023). "The interaction between CD44 and PD-L1 might inspire us to combine therapy to treat gliomas, such as blocking CD44 and other immune checkpoints." (PMID 36776876, 2023). "The miR-21/SP1/DNMT1 positive feedback loop in MSCs triggered by glioma exosomal CD44 could increase MSC exosomal miR-21 to a dozen times that in glioma exosomes, amplifying glioma exosomal immunosuppressive signaling." (PMID 37481646, 2023). "Consequently, we evaluated prognostic value concerning the different CD44 levels in gliomas through Kaplan-Meier analysis." (PMID 36776876, 2023). "The RUNX1/CD44 axis in gliomas remained valuable for further exploration." (PMID 36776876, 2023). "Patients with low expression of CD44 in glioma have better clinical outcomes." (PMID 36835465, 2023). "In this study, we compared the early-passage cell cultures derived from patients’ glioma samples, which were different in their IDH1 R132H mutation status supplemented with dissimilar CD44 expression, to find the peculiar nanomechanical signatures characterizing different brain cancer cells." (PMID 36835465, 2023). "Molecularly, high CD44 expression is associated with gliomas with wild-type (WT) IDH and chromosome 1p/19q noncodeletion, which are biomarkers for aggressive gliomas." (PMID 36989359, 2023). "A stem cell marker CD44 predicts poor prognosis in renal cancers and in gliomas." (PMID 37006265, 2023). "Also, compared to LGG patients, GBM groups showed higher levels of CD44 expression, which demonstrated an adverse role of CD44 in the proliferation and aggressive progress of gliomas." (PMID 36776876, 2023). "And CD44 is vital in aiding the oncogenic process and progression of gliomas." (PMID 36776876, 2023). "In addition, CD44 was found to be lower in expression levels in methylated glioma in the TCGA dataset." (PMID 36776876, 2023). "Therefore, a work of better understanding the CD44 feature in glioma is desperately required to develop a treatment strategy." (PMID 36776876, 2023). "Wingfield applied radiomics features to predict the expression levels of CD44 and CD133 in lower-grade gliomas; In the training and validation sets, the model yielded AUCs of 0.912 and 0.805, respectively, in the CD44 model; 0.912 and 0.816, respectively, in the CD133 model." (PMID 36597144, 2023). "Still, analysis in 1p/19q codeletion pan-glioma showed down-expressed levels of CD44." (PMID 36776876, 2023).
glioma (continued). "The mRNA expression levels of CD44 were significantly up-regulated in gliomas, GBM in particular." (PMID 36776876, 2023). "CD44 expressed by myeloid cells was found to promote the invasion of glioma." (PMID 36776876, 2023). "In our study, the correlation analysis between CD44 and cells in the tumor microenvironment suggested that CD44high glioma cells are inclined to accumulate more inhibitive infiltrating immune cells (helper 2 T cell, regulatory T cell, and immature dendritic cell) into the tumor microenvironment." (PMID 36776876, 2023). "This would imply that in the context of glioma, myeloid CD44 regulates both directly and indirectly MMP9 increase, which could explain the observed drastic effect on this proteinase." (PMID 35992852, 2022). "Thecompounds were then evaluated against glioma-initiating cells by monitoringthe level of CD44+; all the compounds decreased the level of CD44+.The results were further confirmed by in vivo experimentsin the brains of NOD-SCID mice, where compounds decreased the numberof glioma-initiating cells." (PMID 35786935, 2022). "Glioma stem cells (GSCs) show a characteristic CD44+ phenotype and enhanced ALDH activity." (PMID 36231019, 2022). "The risk model (considering CDCP1 combined with CD44 and ITGAM expression) could represent a tool for predicting survival and prognosis in glioma patients." (PMID 35410293, 2022). "Consequently, using zebrafish PDX model we demonstrate that targeting of the CD44 + populations in vivo results in significantly abrogated growth of tumour bulk supporting the efficacy of therapeutic strategies targeting TICs in glioma." (PMID 35840697, 2022). "Careful and detailed evaluation using a plethora of in vitro and in vivo assays demonstrates penetration of this nano-system across the BBB, and CD44-selective and anti-proliferative effects on human glioma, mediated by the downregulation of CD44 receptor levels and its signaling activity." (PMID 35840697, 2022). "A previous study revealed that the specimens of recurrent glioma after radiation therapy activated the expression levels of mesenchymal markers, such as collagen 1A, alpha-smooth muscle actin, CD44, and YKL-40 and reduced the expression of GFAP, a glial marker." (PMID 35448036, 2022). "Among the markers of glioma CSCs are CD44, CD133, and cMyc and increased levels of VEGF expression." (PMID 36428704, 2022). "Targeting CD44 in myeloid cells could modulate their polarization in response to glioma and impede their distinctive pro-tumorigenic ability." (PMID 35992852, 2022). "In the case of 58% of gliomas, an elevated level of soluble CD44 is detected." (PMID 36422293, 2022). "Interestingly, tumour-associated astrocytes increase the migratory ability of glioma cells via up-regulation of glioma cell CD44." (PMID 36555253, 2022). "As cancer stem cells are known to express a high level of CD44, glioma stem cells highly expressing CD44 may participate in the resistance to even the high-dose chemotherapy with BCNU." (PMID 35624954, 2022). "However, up to date little is known about CD44’s role in these cells in regard to glioma progression." (PMID 35992852, 2022). "OPN can activate CD44 by forming a protein complex that could lead to radiation treatment resistance in glioma." (PMID 35954348, 2022). "Furthermore, Ivanova and colleagues have observed that deletion of CD44 hinders invasion of glioma cells into the surrounding brain tissue." (PMID 36555253, 2022). "Furthermore, MT1-MMP can regulate the invasiveness of glioma cells via CD44 expression and restructuring of the actin cytoskeleton." (PMID 35328780, 2022). "It was hypothesized that CD44-mediated transcytosis played a crucial role and allowed deep glioma penetration depending on sequential intra–intercellular delivery via endocytosis–exocytosis." (PMID 35458619, 2022). "However, HA synthesized by 9L glioma cells interacts with CD44 to promote apoptosis of DCs via induction of iNOS." (PMID 33744285, 2021).
glioma (continued). "Glioma patients with IDH1 mutation have median OS three times longer than those without, codeletion of 1p and 19q is associated with better survival rates in glioma, and thus, low CD44 expression patients with glioma may have better clinical outcomes." (PMID 35187044, 2021). "Moreover, another study also showed that the exosome EpCAM promotes the metastasis of glioma by targeting the CD44 signaling molecule on the surface of glioma cells; this exosome influenced the progression of glioma." (PMID 34722277, 2021). "Notably, tumor-initiating cells (TICs) or cancer stem cells (CSCs) are considered to be localized at the perivascular niche in glioma tissues, while CD44 and CSPG4 serve as critical markers of TIC." (PMID 34944101, 2021). "Considering that the brain contains abundant levels of hyaluronic acid, CD44 could play important role in glioma cells’ migration." (PMID 34440169, 2021). "Overall, the inhibition of HAS3 and CD44 decreased glioma cell proliferation in vitro and in vivo." (PMID 33986244, 2021). "The finding of a new candidate biomarker CD44 for M2 TAMs and its immunosuppressive function in glioma is hypothesis-generating and needs more wet experiment validation." (PMID 35187044, 2021). "Additionally, the standard CIBERSORTx pipeline was applied to further evaluate the relationship between CD44 and infiltration of 22 immune cells in glioma microenvironment." (PMID 35187044, 2021). "However, the macrophage-mediated SPP1/CD44 signaling in driving glioma progression has rarely been reported." (PMID 34805184, 2021). "Finally, we showed that high expression levels of both SPP1 and CD44 correlate with an increased infiltration of macrophages and poor prognosis of glioma patients." (PMID 34805184, 2021). "Considering the mesenchymal GBM subtype is featured with more infiltrating tumor-associated macrophages (TAMs) and immunosuppression, we speculated that CD44 may play an important role in glioma immune environment." (PMID 35187044, 2021). "Additionally, the IHC data of normal brain tissues and glioma samples reveal that high-grade glioma has the highest CD44 protein expression level, but that the normal brain tissue has the lowest CD44 expression." (PMID 35187044, 2021). "CD44 expression suppressed ferroptosis in cancer cells and might exert its function as a glioma promoter by increasing tumor cell invasion and proliferation, which therefore could be a promising therapeutic target." (PMID 34819946, 2021). "Together, these results suggest that CD44 functions as a CSPG in glioma cells, and that CS chains may be involved in facilitating CD44 and integrin cooperation on adhesion complexes." (PMID 34944101, 2021). "Notably, siRNAs were used to silence HAS3; alternatively, CD44 antibody was added to the culture media of glioma cells." (PMID 33986244, 2021). "To go a step further, we explored the immunosuppressive role of CD44 in glioma." (PMID 35187044, 2021). "We thus hypothesized that targeting CS chains by knockdown of CHSY1 or treating glioma cells with C6S binding peptides may result in decreased CD44 protein levels, and inhibit the outside-in signals from regulating the gene expression of integrins." (PMID 34944101, 2021). "In addition, the peptide demonstrated significant affinity to CD44, promoted CD44 degradation, and suppressed integrin β1 expression in glioma cells." (PMID 34944101, 2021). "However, it still needs more clinical studies to confirm the relationship between CD44 and glioma immunotherapy for the small number of glioma samples treated with immunotherapy." (PMID 35187044, 2021). "Therefore, there are some positive relationships between CD44 and these immune checkpoints in glioma." (PMID 35187044, 2021). "CD44 can also mediate glioma cell adhesion to hyaluroonic acid in the ECM and invasion in vitro." (PMID 33834020, 2021).
glioma (continued). "Collectively, these findings indicated that the macrophage-mediated SPP1/CD44 interaction might contribute to the induction of MES-like glioma cells." (PMID 34805184, 2021). "Moreover, inhibition of HAS3 or treatment with the CD44 antibody decreased the expression of Ki67 in U251 or LN229 glioma cells, respectively." (PMID 33986244, 2021). "Therefore, our findings highlighted the importance of targeting SPP1/CD44-mediated macrophage-tumor cell interaction in anti-glioma treatment." (PMID 34805184, 2021). "Therefore, we investigated the effect of silencing HAS3 or treatment with CD44 antibodies on glioma cell cycle arrest." (PMID 33986244, 2021). "CD44 is also associated with the specific binding of glioma cells to HA, but it is not the only receptor involved." (PMID 33744285, 2021). "Based on the results, we speculate that there may be a lncRNA-miRNA-gene network among lncRNA TMEM161B-AS1, hsa-miR-27a-3p, FANCD2 or CD44, which involves in the occurrence of gliomas." (PMID 34689169, 2021). "Similarly, high CD44 expression has also been reported to drive glioma progression and correlate with poor prognosis of GBM patients." (PMID 34805184, 2021). "This suggests that early mechanotransduction may occur via an CD44-independent ligand-mediated mechanism whereas the well-described ECM-integrin interactions in glioma may occur later." (PMID 35127517, 2021). "Thus, glioma-infiltrating CD44+ T cells can inhibit antitumor immunity by inducible expression of PD-L1." (PMID 35187044, 2021). "Similarly, high CD44 expression was observed to correlate with decreased overall survival time of glioma patients." (PMID 34805184, 2021). "To answer the question whether CD44 is involved in malignant progress of glioma, we compared its expression level in different WHO grades, IDH types, 1p19q states, and recurrent status in TCGA and CGGA glioma mRNA-seq datasets." (PMID 35187044, 2021). "Finally, we investigated the clinical significance of increased expression of SPP1 and CD44 in glioma." (PMID 34805184, 2021). "Notably, the SPP1/CD44 signaling in the perivascular niche has been shown to promote the stem cell-like properties and radiation resistance of glioma cells." (PMID 34805184, 2021). "In addition, WHO grades II and III patients with glioma with high CD44 mRNA expression faced poor survival compared to low CD44 mRNA level in an independent manner." (PMID 35187044, 2021). "In addition, we built the regulon network of glioma cells, and the regulon network of CD44+ cells is different from CD44- cells." (PMID 35187044, 2021). "Moreover, it was demonstrated that optimal levels of CD44 were necessary on GBM cells to generate highly infiltrative tumors in a mouse model and that treatment with an anti-CD44 monoclonal antibody inhibited tumor growth of local glioma in a mouse model." (PMID 33744285, 2021). "Overall, HA, HAS3, and CD44 levels are significantly increased in glioma tissues and may play important roles in glioma progression." (PMID 33986244, 2021). "Importantly, using a CS-binding peptide that suppresses glioma invasiveness and inhibits integrin and CD44 cooperation, we highlighted the therapeutic potential of targeting CS in human glioma." (PMID 34944101, 2021). "Thus, approaches that interfere with HA metabolism by altering the expression of HAS3 and CD44 and the administration of 4-MU potentially represent effective strategies for glioma treatment." (PMID 33986244, 2021). "Moreover, the key CS synthase, CHSY1, regulates the expression of integrins and modifies CS chains on CD44 in glioma cells." (PMID 34944101, 2021). "Subsequent subgroup analyses showed that disease stages may affect the potential prognostic efficacy of tumor CD44 expression for the survival in patients with glioma." (PMID 32232385, 2020). "The prognostic value of CD44 expression in gliomas was inconsistent." (PMID 33381460, 2020).